SACS (sacsin molecular chaperone)
Diseases named in the same sentence as SACS in open-access papers:
SACS is named in the same sentence as 59 diseases in open-access papers, as found by Europe PMC text mining. Sharing a sentence is not in itself a finding about the gene and the disease. The quoted sentences say what the papers report.
Autosomal recessive spastic ataxia of Charlevoix-Saguenay (18 papers, 2010 to 2025). "Autosomal Recessive Spastic Ataxia of Charlevoix-Saguenay (ARSACS) is a rare genetic disorder caused by mutations in the SACS gene." (PMID 40304869, 2025). "Autosomal recessive spastic ataxia of Charlevoix-Saguenay (ARSACS) is caused by mutations in SACS gene encoding sacsin, a huge protein highly expressed in cerebellar Purkinje cells (PCs)." (PMID 37159335, 2023). "Autosomal Recessive Spastic Ataxia of the Charlevoix Saguenay (ARSACS) is caused by mutation in the SACS gene resulting in loss of function of the protein sacsin." (PMID 36555380, 2022). "Autosomal recessive spastic ataxia of Charlevoix-Saguenay (ARSACS) is a rare early-onset neurodegenerative disease associated with mutations in the SACS gene, which encodes sacsin, a 520 kDa multidomain protein." (PMID 34445111, 2021). "Autosomal Recessive Spastic Ataxia of Charlevoix-Saguenay (ARSACS) is caused by mutations in the gene SACS, encoding the 520 kDa protein sacsin." (PMID 28535259, 2017). "Spastic Ataxia Charlevoix-Saguenay (SACS) is the gene most frequently associated with ARSACS (cytogenetic location: 13q12; molecular location on chromosome 13: base pairs 23,902,964 to 24,007,840)." (PMID 21850161, 2011). "Autosomal recessive spastic ataxia of Charlevoix-Saguenay (ARSACS) is a progressive ataxic disorder caused by mutations in the SACS gene located on chromosome 13q12.12." (PMID 36576926, 2022). "Autosomal recessive spastic ataxia of Charlevoix-Saguenay (ARSACS) is a multisystem hereditary ataxia associated with mutations in SACS, which encodes sacsin, a protein of still only partially understood function." (PMID 34445111, 2021). "Autosomal recessive spastic ataxia of Charlevoix-Saguenay (ARSACS) is a rare neurodegenerative disorder caused by biallelic mutations in the SACS gene." (PMID 33414805, 2020). "Autosomal recessive spastic ataxia of Charlevoix-Saguenay (ARSACS [MIM 270550]) is an early-onset neurodegenerative disorder caused by mutations in the SACS gene." (PMID 30866998, 2019). "Autosomal recessive spastic ataxia of Charlevoix-Saguenay (ARSACS) is the second most frequent recessive ataxia and caused by mutations in the SACS gene on chromosome 13q12." (PMID 34649570, 2021). "Autosomal recessive spastic ataxia of Charlevoix-Saguenay (ARSACS) is due to a deficit in the chaperone protein sacsin (SACS)." (PMID 20808545, 2010). "Autosomal Recessive Spastic Ataxia of the Charlevoix Saguenay (ARSACS), the second most common recessive ataxia worldwide, is a childhood-onset neurodegenerative disease caused by over 200 different mutations in the SACS gene." (PMID 36555380, 2022). "Autosomal-recessive spastic ataxia of Charlevoix-Saguenay (ARSACS) is a progressive neurodegenerative disorder caused most often by a deletion mutation in the SACS gene encoding the large (521 kD) protein sacsin that functions as a chaperone and regulates the cytoskeleton." (PMID 34970120, 2021).
Ataxia (14 papers, 2013 to 2025). Ataxia refers to impaired coordination of voluntary muscle movement. "A recent case of another compound heterozygous SACS mutation, c.7272C>A:p.(C2424*) and c.11319_11321del:p.(R3774del), was found in a patient with cerebellar ataxia with migraine." (PMID 35008978, 2022). "In the Dutch population, SACS mutations seemed to be quite prominent in patients with early-onset cerebellar ataxia." (PMID 35008978, 2022). "Similarly, in another patient (ID: 9400f), who displayed ataxia and spastic gait, we observed a novel SACS p.Ser2711Leu variant (NM_014363.5:c.8132C > T) in compound heterozygous configuration with a known pathogenic variant (p.Arg2502∗; ClinVar ID: 5513)." (PMID 31920494, 2019). "SACS mutations were responsible for at least 11% (9/83) of patients with unexplained ataxia." (PMID 23497566, 2013). "In sum, we here demonstrate that each feature of the classical ARSACS triad (cerebellar ataxia, spasticity, peripheral neuropathy, Charlevoix-Saguenay origin) might in fact be missing in patients with SACS mutations, so the name might be misleading." (PMID 23497566, 2013). "The most frequent genes were those associated with spastic ataxia, ataxia, and neuropathy or AOA: SACS (4 families, 21.1%), KIF1C (2 families, 10.5%), and PNKP (3 families, 15.8%); the remaining genes were identified in single families only." (PMID 35326432, 2022). "The most frequent causal genes were associated with spastic ataxia (SACS and KIF1C) and with ataxia and neuropathy or AOA (PNKP)." (PMID 35326432, 2022). "The huge size of the SACS gene complicates the screening of patients presenting atypical clinical phenotype and indicates that this form of ataxia may be under-diagnosed in several populations, including ours." (PMID 26068213, 2015). "As the symptoms worsened rapidly, a novel SACS mutation (c.4003 G>A, p.1335 Val>Ile, Heterozygous) was discovered using WES, although no pathogenic mutations with low frequency were found in ataxia-related genes, such as SPG7, FXN, and GFAP." (PMID 38132465, 2023). "In this study, a novel SACS mutation (p.Val1335IIe, Heterozygous) was identified in a Korean patient in their 50s with late-onset ARSACS characterized by cerebellar ataxia and spasticity without peripheral neuropathy." (PMID 38132465, 2023). "Further, we demonstrate that ARSACS (gene: SACS; n = 6, 22.2%), SCAR8 (gene: SYNE1; n = 5, 18.5%), SCAR9 (gene: ADCK3; n = 5, 18.5%) and AOA2 (gene: SETX; n = 4, 14.8%) are the most common recessive ataxia subtypes in the Chinese population." (PMID 34663476, 2021).
autosomal recessive spastic ataxia (12 papers, 2013 to 2026). Autosomal recessive form of spastic ataxia. "Mutations in the SACS gene are associated with autosomal recessive spastic ataxia of Charlevoix-Saguenay disease (ARSACS) or complex clinical phenotypes of Charcot-Marie-Tooth disease (CMT)." (PMID 38928084, 2024). "The study involves eight patients with autosomal recessive spastic ataxia of Charlevoix–Saguenay (including a novel case) carrying variants of different types and positions along the SACS gene and two parents who are carriers of heterozygous missense variants." (PMID 39091421, 2024). "Autosomal recessive spastic ataxia of Charlevoix–Saguenay is a rare neurodegenerative disease caused by biallelic variants in the SACS gene encoding for sacsin." (PMID 39091421, 2024). "Mutations in SACS cause autosomal recessive spastic ataxia of the Charlevoix–Saguenay type, the second most common cause of recessive ataxia, with >300 mutations described worldwide according to HGMD." (PMID 35328054, 2022). "Recessive variants in SACS induces a childhood onset spastic ataxia disorder, autosomal recessive spastic ataxia of Charevoix-Saguenay." (PMID 33426505, 2020). "We identified a novel mutation in exon 10 of the SACS gene: c.7962T>G p.(Tyr2654*), establishing the diagnosis of autosomal recessive spastic ataxia of Charlevoix-Saguenay (ARSACS)." (PMID 27600236, 2015). "All patients were compound heterozygous (c.13352T>C, p.Leu4451Pro; c.6890T>G, p.Leu2297Trp) for mutations in the SACS gene establishing the diagnosis of autosomal recessive spastic ataxia of Charlevoix-Saguenay (ARSACS)." (PMID 23785480, 2013). "SACS mutations are cause of autosomal recessive Spastic ataxia, Charlevoix-Saguenay type." (PMID 37180992, 2023). "A 38-year-old woman was diagnosed autosomal recessive spastic ataxia of Charlevoix-Saguenay (ARSACS) with a novel pathogenic variant in the SACS gene presented with gradually progressive spastic ataxia since the age of 2 years; then, she became wheelchair-bound at the age of 28 years." (PMID 32775015, 2020).
spastic ataxia (12 papers, 2012 to 2025). "Mutations in SACS cause spastic ataxia of Charlevoix–Saguenay, a rare autosomal recessive neurodegenerative disorder characterized by early-onset spasticity, progressive cerebellar ataxia, and peripheral neuropathy." (PMID 40243517, 2025). "We identified one proband with two homozygous missense variants, p.(Gly4230Ser) and p.(Leu4221Val) in SACS with a relatively slowly progressive recessive spastic ataxia with onset in the teens." (PMID 28362824, 2017). "Mutations in the SACS gene lead to the human disease spastic ataxia of Charlevoix-Saguenay, and it is known that the very large sacsin protein (4579 amino acid residues) encoded by SACS possesses heat shock protein (HSP)-like ATPase domains and HSP-like activity." (PMID 22928584, 2012). "In this study, there was no causative mutation associated with spastic ataxia, such as SACS/VAMP1/KIF1C/MARS2/MTPAP/AFG3L2(AR), detected." (PMID 35572931, 2022). "Spastic ataxia of Charlevoix-Saguenay is a neurodegenerative condition due to mutations in the SACS gene and without a cure." (PMID 32466761, 2020). "Additionally, individuals with deletion of the entire SGCG gene also lacked five other genes, among which SACS and MIPEP are reported to cause spastic ataxia and combined oxidative phosphorylation deficiency 31, respectively." (PMID 39755676, 2025).
hereditary ataxia (4 papers, 2021 to 2024). An instance of an atactic disorder that is caused by an inherited genomic modification in an individual. "SACS and SYNE1 mutations have been observed mainly in Quebec and Canada, where ARSACS and SCAR8 are the second and third most common hereditary ataxia, respectively." (PMID 34663476, 2021).
viral disease (3 papers, 2012 to 2024). "SACS mRNA was shown by QPCR to be up-regulated by asymptomatic high nodavirus carrier state and IP pIC treatment in brains of cod and by ISA (Infectious Salmon Anemia) virus infection in salmonid TO cells." (PMID 22928584, 2012). "Additional powerful biomarkers were identified for Pacific (Trim21, IFI) and Atlantic (CD9, RAD1, SACS, XAF1) salmon whereby assays did not work across species; if re-designed, these biomarkers may also contribute to the universal separation of viral disease states across species." (PMID 28702195, 2017).
Arrhythmia (2 papers, 2011 to 2022). Any cardiac rhythm other than the normal sinus rhythm. "The venom peptide (known as GsMtx-4) works directly blocking the excitatory (action on stretch-activated ion channels; SACs) currents responsible for arrhythmia." (PMID 21450096, 2011). "The mechanoelectrical feedback (MEF) mechanism in the heart that plays a significant role in the occurrence of arrhythmias, involves cation flux through cation nonselective stretch‐activated channels (SACs)." (PMID 35384354, 2022).
autism (2 papers, 2018 to 2022). Persistent deficits in social interaction and communication and interaction as well as a markedly restricted repertoire of activity and interest as well as repetitive patterns of behavior. "Case 11 was a 14-year-old boy with two known SACS mutations and a clinical picture of ID, autism, epileptic encephalopathy." (PMID 35328054, 2022).
colorectal cancer (2 papers, 2022 to 2023). A primary or metastatic malignant neoplasm that affects the colon or rectum. "Another genomic feature that is present recurrently among the abnormalities conferring BRAF inhibitor sensitivity in colorectal cancer cell lines is mutations in SACS, a gene encoding for sacsin, a chaperone protein." (PMID 36295658, 2022). "Unrelated molecular alterations associated with sensitization of colorectal cancer cell lines to BRAF inhibitors included mutations in SACS, encoding for chaperone protein sacsin and deletions at the locus of parkin." (PMID 36295658, 2022). "Besides BRAF mutations, BRAF inhibitor sensitivity in colorectal cancer cell lines is conferred by SACS mutations and PRKN locus loss." (PMID 36295658, 2022). "Among colorectal cancers classified as MSI high or with proofreading polymerase epsilon mutations, SACS mutations are present in 42.5% of cases, suggesting that these mutations are associated with high TMB and may be passenger." (PMID 36295658, 2022). "Mutations in SACS have not been previously linked with colorectal cancer." (PMID 36295658, 2022).
adenoma (1 paper, 2019). A neoplasm arising from the epithelium. "We then investigated the accumulation of mutations in SACs of normal or adenoma-adjacent tissue in 15 cancer-related genes among each CCS group." (PMID 30785889, 2019).
age-related macular degeneration (1 paper, 2012). Age-related loss of vision in the central portion of the retina (macula), secondary to retinal degeneration. "Two of these genes have been related to ophthalmologic disorders, including age related macular degeneration (HMCN1) and keratoconus (VSX1) and several have been related to neurologic disorders (IKBKAP, SGCG, SACS, ARHGEF10, and CACNA1S)." (PMID 23139751, 2012).
Cerebellar atrophy (1 paper, 2023). Cerebellar atrophy is defined as a cerebellum with initially normal structures, in a posterior fossa with normal size, which displays enlarged fissures (interfolial spaces) in comparison to the foliae secondary to loss of tissue. "Brain MRI was performed after two pathogenic SACS variants were detected by WGS, and prominent cerebellar atrophy was revealed." (PMID 37180992, 2023).
Cerebral atrophy (1 paper, 2025). Atrophy (wasting, decrease in size of cells or tissue) affecting the cerebrum. "Other findings may involve corpus callosum thinning, mild cerebral atrophy, and T2 hyperintensities in the periventricular white matter, reflecting the widespread neurodegeneration associated with SACS mutations." (PMID 40243517, 2025).
diabetes (1 paper, 2024). "Our model not only demonstrates a state-of-the-art T2D predictive capacity that can potentially be implemented for clinical diagnostics but also provides novel biomarkers such as SACS DNA methylation that we recently linked to diabetes pathogenesis." (PMID 38918439, 2024).
head and neck squamous cell carcinoma (1 paper, 2020). A squamous cell carcinoma that arises from any of the following anatomic sites: lip and oral cavity, nasal cavity, paranasal sinuses, pharynx, larynx, and salivary glands. "For example, SACS, a DNAJC (HSP40) member, promoted both cell proliferation and EMT in 12 cancer types, including BLCA, head and neck squamous cell carcinoma (HNSC), and LUAD." (PMID 33225964, 2020).
Intellectual disability (1 paper, 2025). "Clinical clues to pinpoint the causative gene from the heterogeneous CMT2 and AR‐CMT2 group included pyramidal signs in SACS, MTRFR, and HSPB1, vocal cord paralysis in TRPV4, intellectual disability in MCM3AP, late disease onset in MME, in accordance with previous reports." (PMID 39776111, 2025).
neuroblastoma (1 paper, 2020). Neuroblastoma (NB) is the most common solid, extracranial childhood tumor. "In this study, we analyzed proteomics data obtained using the SomaLogic technology, comparing cell lysates from ARSACS patients and from a SACS KO SH-SY5Y neuroblastoma cell model." (PMID 33584503, 2020).
neuronal ceroid lipofuscinosis type 7 (1 paper, 2022). "A homozygous deletion of exon 2 of the MFSD8 gene is associated with neuronal ceroid lipofuscinosis type 7 and a homozygous deletion of 16 exons in PARK7 was detected in a child with pathogenic SACS mutations." (PMID 34791078, 2022).
neurodegenerative disease (6 papers, 2022 to 2024). A disorder of the central nervous system characterized by gradual and progressive loss of neural tissue and neurologic function. "Autosomal recessive SACS–Saguenay (ARSACS) is a rare early-onset neurodegenerative disease caused by mutations in the SACS gene, encoding sacsin." (PMID 38825675, 2024). "This review introduces the genetic mutations discovered in the SACS gene and discusses its pathomechanisms and its possible involvement in other neurodegenerative diseases." (PMID 35008978, 2022). "The involvement of the SACS gene in other neurodegenerative diseases, such as AD, PD, ALS or CJD, has not been reported yet." (PMID 35008978, 2022).
cancer (5 papers, 2018 to 2022). A tumor composed of atypical neoplastic, often pleomorphic cells that invade other tissues. "The expression of SELE and SACS increased considerably in cancer samples compared to normal samples, according to the results of RT-qPCR data (P < 0.01)." (PMID 36064367, 2022). "Predicted interaction between SACS or SCN10A proteins and chemotherapy drugs, cyclophosphamide/piroxicam, was exhibited in the present study via several cytochrome P450 (CYP) proteins which plays an important role in cancer development and response to therapy." (PMID 30001383, 2018).
neurologic disorders (3 papers, 2012 to 2025). "Autosomal Recessive Spastic Ataxia of Charlevoix-Saguenay (ARSACS) is an early-onset neurological disorder caused by mutations in the SACS gene, resulting in the loss of sacsin function." (PMID 40389788, 2025). "Autosomal recessive spastic ataxia of Charlevoix–Saguenay (ARSACS) is a neurological disease with mutations in SACS, encoding sacsin, a multidomain protein of 4,579 amino acids." (PMID 23280630, 2013).
tumor (3 papers, 2018 to 2024). "Conversely, only four of the thirteen deletions that resulted in a significant decrease in expression in tumors were previously identified as down-regulated when comparing normal and tumor tissue (CRYAB, SACS, HSPB7, and HSPB2)." (PMID 38816397, 2024). "We expected that the four genes (SACS, LRP2, WDR87, and XIRP2) that were detected in all POLE category tumours with POLE p.P286R or p.V411L would exhibit high PS if this score reflected an accumulation of biased mutation patterns." (PMID 29880869, 2018). "Furthermore, as compared to normal samples, tumor samples had higher levels of SELE and SACS expression, and tumor samples had a wide range of expression for these genes." (PMID 36064367, 2022).
infection (2 papers, 2014 to 2022). The state of being infected such as from the introduction of a foreign agent such as serum, vaccine, antigenic substance or organism. "The most induced genes after NNV infection with the wt virus were VRGs, particularly RTP3, SACS, and TRIM39." (PMID 35215144, 2022).
metabolic disease (1 paper, 2023). A congenital disorder (due to inherited enzyme abnormality) or acquired (due to failure of a metabolically important organ) disorder resulting from an abnormal metabolic process.
SACS also shares sentences with these, for which no sentence is quoted: cerebellar ataxia (5 papers); peripheral neuropathy (5); neuropathy (4); progressive ataxia (3); breast carcinoma (2); Friedreich ataxia (2); hereditary spastic paraplegia (2); Adult onset (1); Alexander disease (1); arachnoid cyst (1); Cerebellar Ataxia, Neuropathy, Vestibular Areflexia Syndrome (1); cerebral palsy (1); channelopathy (1); Charcot-Marie-Tooth disease (1); cognitive decline (1); Cognitive impairment (1); distal motor neuropathy (1); Dystonia (1); epilepsy (1); Epileptic encephalopathy (1); hereditary motor and sensory neuropathy (1); keratoconus (1); Limb tremor (1); limb-girdle muscular dystrophy type 1D (1); mitochondrial disease (1); muscular dystrophy (1); phenylketonuria (1); rectal cancer (1); retinal disorder (1); schizophrenia (1).
A further 5 diseases each share a sentence with SACS in 1 paper.